IL6 (interleukin 6)
Diseases named in the same sentence as IL6 in open-access papers (continued):
Sharing a sentence is not in itself a finding about the gene and the disease.
psychiatric disorder (continued). "A considerable body of evidence suggests that many neurological and psychiatric disorders are accompanied by disorders of IMs, like interleukin (IL)-1b, IL-2, IL-6, interferon (IFN), tumor necrosis factor a (TNF a), the soluble IL-6 receptor (sIL-6R), and the IL-1 receptor antagonist (IL-1RA)." (PMID 38674921, 2024). "In addition, the overactivated inflammatory processes (such as IL-1, IL-6, IL-15, and TNFα) that observed among both OA patients and patients with psychiatric disorders implied the possibility of shared biological pathways between these two traits." (PMID 40224608, 2023). "Meanwhile, IL-6 plays a critical role in psychiatric disorders like MDD and SCZ." (PMID 35509074, 2022). "Thus, multiple lines of evidence link inflammatory factors, specifically IL-6, with mental illness and related symptomology." (PMID 27206977, 2016). "Pro-inflammatory cytokines, such as tumor necrosis factor-alpha (TNF-α), interleukin-6 (IL-6), and interleukin-1β (IL-1β), are implicated in both the pathogenesis of IBD and the onset of psychiatric disorders, suggesting that systemic inflammation may underlie the comorbidity of these conditions." (PMID 40823034, 2025). "Therefore, we speculate that mental illness may affect the development of IS in B cells and IL-6 in T cells." (PMID 37305753, 2023). "Additionally, shared etiologies were also a rational speculation, since overactivated inflammatory factors (such as IL-1, IL-6, IL-15, and TNFα) and altered immune response were observed among both OA and psychiatric disorders patients." (PMID 40224608, 2023). "Therefore, scientific evidence suggests that IL-6 pathway may be a new target for diagnosing and treating mental disorders." (PMID 36225733, 2022). "Cytokines like IL-6 influence the biochemical mechanisms of other cells, e.g., their inflammatory responses and the concentration of neurotransmitters, thus might have an additional indirect impact on psychiatric disorders." (PMID 33238940, 2020). "Plasma IL-6 was also positively correlated with tph2 mRNA expression in the dorsomedial DR (cDRD), corroborating the hypothesis that proinflammatory cytokines interact with dysregulated neuronal function in psychiatric disease." (PMID 29520369, 2018). "Elevated levels of pro-inflammatory cytokines such as interleukin-6 (IL-6) and tumor necrosis factor-alpha (TNF-α) are frequently observed in individuals with psychiatric disorders." (PMID 40141685, 2025). "CRP and many serum cytokines levels have been recently suggested as biological biomarkers of psychiatric diseases and skin diseases such as TNF-α, IL-1β, IL-6, and IL-18." (PMID 39624485, 2024). "Previous studies noted higher blood levels of inflammatory biomarkers (including IL-6, IL-1β, TNF-α, and CRP) in people with mental illness who have suicidal attempts in comparison to healthy controls or non-suicidal people with mental illness." (PMID 39882160, 2024). "It has been suggested that dysregulation of cytokines, particularly IL-1-β, IL-6, IL-10, interferon (IFN-γ), and TNF-α, contributes to the pathogenesis of certain psychiatric disorders." (PMID 37644934, 2023). "In fact, it is clear from the literature that the increase in proinflammatory cytokines, such as IL-1, IL-6 and TNF-α, and imbalances in T cells are directly responsible for the development of psychiatric disorders." (PMID 36835652, 2023). "Genes of pro-inflammatory cytokines IL-1β, IL-6, and TNF were significantly upregulated in MSB macaques, which was similar to results from human psychiatric disorder studies." (PMID 34394017, 2021). "Antidepressants are hypothesized to treat mental illness via immunoregulatory pathways, by decreasing levels of pro-inflammatory cytokines such as TNF52, IL-6, IL-1β, and IL-10." (PMID 39941688, 2025).
psychiatric disorder (continued). "Further elucidation of the mechanisms underlying the relationship between IL-6 and ROS in reactive microgliosis could provide insights not only into the side effects of drugs, but also into the pathogenesis and development of neurodegenerative and psychiatric disorders." (PMID 39652148, 2025). "Interestingly, an imbalance in cytokines such as IL-6, TNF, IFN-γ, MIF, IL-17, TGF-β1, and IL-8 are correlated to psychiatric disorders." (PMID 40333139, 2025). "The activation of these innate immune mechanisms, including proinflammatory cytokines, such as IL-1, IL-6, TNF-α, and CRP, may contribute to the development of psychiatric disorders." (PMID 38742123, 2024). "Inflammatory cytokines or other inflammatory stimuli (e.g., IL-1β, IL-4, IL-6, TNF-α, and MCP-1) induce depressive symptoms or other psychiatric disorders, and these factors may also predict the development of these disorders." (PMID 33536923, 2020). "The elevation of peripheral IL-1β, IL-6 and TNF-α could be a potential biomarker of vulnerability for psychiatric disorders in adults but their roles remain unknown for elderly." (PMID 30104698, 2018). "The proportion of patients with any psychiatric disorders did not moderate the associations between childhood trauma and CRP (t=0.02, P=0.98, I2res=74.0%, τ2=0.007), IL-6 (t=0.23, P=0.82, I2res=48.5%, τ2=0.006) or TNF-α (t=0.54, P=0.61, I2res=42.7%, τ2=0.01)." (PMID 26033244, 2016). "Elevated CSF IL‐6 level is a potential marker that may reflect the neuroinflammatory subpopulation and basic negative valence symptoms across psychiatric disorders." (PMID 39317977, 2024). "Genotyping patients for IL6R rs2228145 while measuring their IL6 and CRP levels could be useful tools as non-specific diagnostic markers of alcohol- addicted patients with comorbid psychiatric disorders." (PMID 38275640, 2023). "Finally, using a wider selection of inflammatory markers, rather than being limited to only CRP and IL-6, will also help in understanding which inflammatory pathways are important in the context of psychiatric disorders." (PMID 36277463, 2022). "Furthermore, alterations in cytokine secretion, such as increased levels of the inflammatory markers interleukin-6, TNF-a, and C-reactive protein, which contribute to dysfunctional immune responses, is another possible mechanism by which exposure to psychiatric disorders may be related to CRC risk." (PMID 41530201, 2026). "This study also replicates and extends the literature on the relationship between neuroticism, the L/A ratio, adiponectin, CRP, IL-6 and TNF-α by focusing on previously unaddressed populations: young adults with and without psychiatric disorders." (PMID 33963214, 2021). "Recently published systematic review and meta-analysis evaluated the peripheral levels of pro-inflammatory markers including IL-1β, IL-6, TNF-α, and CRP between the elderly with AD and controls without any psychiatric disorder." (PMID 31277647, 2019). "For example, studies have found higher levels of inflammatory markers including interleukin 6 (IL-6), a multifunctional cytokine, and C-reactive protein (CRP), an acute phase protein, among clinical patients with psychiatric disorders compared with individuals without these disorders." (PMID 30987624, 2019).
kidney (142 papers, 2004 to 2026). "Studies of human kidney transplant recipients have found increased levels of IL-6 in the serum, urine, and biopsy tissue linked to inflammatory cell infiltration during renal allograft rejection." (PMID 38993849, 2023). "Although we observed the associations between interleukin 6 or procalcitonin and kidney function in studied kidney transplant recipients, the associations were weaker and less consistent than that between sCD93 and kidney graft function." (PMID 34827620, 2021). "In addition, it has been reported that excess adipose tissue in obese individuals can further increase inflammatory mediators (e.g., interleukin 6), which have been shown to be associated with impaired lung function." (PMID 36902630, 2023). "IL-6 is generated by the activation of different cells in the lung tissue, including alveolar macrophages and endothelial cells, due to various stimuli, such as stretching, which are closely associated with lung injury and lung inflammation." (PMID 24137265, 2013). "Evidence consistently demonstrated that redox-sensitive pathways-including NF-κB, NRF2, and IL-6/JAK/STAT3-drive colorectal carcinogenesis by promoting genomic instability, immune evasion, angiogenesis, and therapy resistance." (PMID 41900943, 2026). "Due to the substantial hypoglycemic effect and antioxidant property combination of banaba+policosanol, the latter effectively protected against fatty liver changes and hepatic IL-6 generation in the diabetic hyperlipidemic zebrafish." (PMID 40143139, 2025). "Although scientific data on these compounds remain scarce, previous reports and current findings indicate their potential to modulate interleukin-related signaling pathways (IL-6 and IL-8), which play key roles in inflammation and colorectal carcinogenesis." (PMID 41256010, 2025). "Kidney inflammation indices (IL-1β, IL-6 and P-STAT3) were significantly decreased in CKD-DTBN as compared to CKD mice." (PMID 38555397, 2024). "The present findings showed that RC significantly inhibited the levels of MCP-1, TNF-α, and IL-6, thereby decreasing the level of liver inflammation in NAFLD." (PMID 36660274, 2023). "When tubular epithelial cells were stimulated with several inflammatory cytokines, including TNF‐α, interleukin (IL)-1β, and IL-6, EMT was facilitated in the development of allograft kidney IF; however, the underlying mechanisms remained ambiguous." (PMID 37507403, 2023). "The authors summarize that inhibition of IL-6 is a novel and promising treatment option to regulate T-cell mediated immune responses in kidney transplant recipients." (PMID 35497778, 2022). "Reports have shown that kidney transplant recipients frequently exhibit elevated serum and urinary IL-6 levels after transplantation and during rejection episodes." (PMID 35497778, 2022). "Collectively, our results provided novel insight into the downstream mechanism of the IL-6 signaling pathway in PM-induced aorta inflammation, that is, ICAM-1 and VCAM-1-dependent monocyte adhesion." (PMID 34336088, 2021). "Here we got similar results as a recent study that hippocampal and serum levels of TNF-α, IL-1β, IL-6 were elevated accompanied by a drop in IL-10 level 24 h after middle cerebral artery occlusion in rats." (PMID 32848589, 2020). "• Animal studies demonstrate that urine IL-6 increases significantly in acute kidney injury due to acute tubular necrosis (ischemia and cisplatin), but not pre-renal azotemia." (PMID 20942931, 2010). "In the process of kidney injury, M1 macrophages promote inflammation and tubular cell apoptosis by secreting pathogenic factors such as IL-1β, TNF-α and IL-6; however, M2 macrophages reduce inflammation and promote renal recovery by secreting trophic factors such as IL-10, TGF-β and arginase-1." (PMID 38785317, 2024). "In addition, the levels of tumour necrosis factor (TNF)-α, and interleukin (IL)-6 were measured to assess inflammation and was estimated kidney oedema." (PMID 37378741, 2023).
kidney (continued). "There is also evidence suggesting a role for IL-6 in liver inflammation and fibrosis, and the metabolomic profile observed in this study is suggestive of altered liver vascular homeostasis, a typical manifestation of liver pathologies." (PMID 37298645, 2023). "The cytokine theory is a mainstream theory in the research of radiation lung injury; it is also a hot spot of current research, and the cytokines that cause radiation lung injury mainly include tumor necrosis factor-α (TNF − α), interleukin-6 (IL-6), transforming growth factor (TGF − β1), and so on." (PMID 35002569, 2021). "The purpose of our work was to explore the potentials of CORM-2 in the inhibition of PM-induced IL-6 expression, monocyte adhesion, and HASMC migration, which are hallmarks of vascular inflammation (e.g., aorta inflammation) implicated in many VCDs, as well as the underlying mechanisms." (PMID 34336088, 2021). "FGF10 is known to protect neurons against oxygen-glucose deprivation injury in vitro, and FGF10 treatment depressed the triggered inflammatory factors of the TNF-α, IL-6, and nuclear factor-κB signaling pathways in a mouse middle cerebral artery occlusion model." (PMID 34383782, 2021). "Additionally, mTOR-deficient mice showed greater expression levels of inflammation-related genes such as MCP-1, TNF-α, and IL-6 than wild-type (WT) mice after liver IR via negatively modulating NF-κB." (PMID 31827701, 2019). "However, the CR kidney transplant patients had significantly elevated levels of proinflammatory cytokines IL-2 (P = 0.005), IL-1β (P = 0.05), and IL-6 (P = 0.05)." (PMID 24741575, 2014). "In addition, IL-6 contributed to the anti-inflammatory effect, suggesting that it suppressed age-related fatty degeneration of the liver, in line with previous findings that exercise-induced IL-6 might have an anti-inflammatory effect because it induces IL-10." (PMID 38999780, 2024). "We compared markers of kidney inflammation and injury (neutrophil gelatinase-associated lipocalin, kidney injury molecule-1) as well as plasma and urine levels of T cell-associated cytokines (TNF-α, interferon-γ, interleukin (IL)-2, IL-4, IL-6, IL-8, IL-9, and IL-10) between groups." (PMID 36938084, 2023). "Notably, some studies have indicated that upregulation of IL-6/JAK/STAT3 signaling is one of the most important pathways involving in colorectal tumorigenesis and plays a pivotal role in the whole developmental processes, including initiation, development and formation in CRC." (PMID 28591704, 2017). "The levels of IL-1β, IL-6, and TNF-α were measured to investigate the impact of SP nutritional intervention on liver inflammation in ALD mice." (PMID 40362898, 2025). "In this study, CC inhibited the increased expression of MCP-1, IL-6, IL-1β, COX-2, ICAM-1, and F4/80 in AD-induced kidney injury." (PMID 37513959, 2023). "Oolong tea down regulated IL-6 and up regulated the expression of IL-10 to alleviate alcoholic liver injury, while white tea down regulated TNF-α and IL-6 and up regulated IL-10." (PMID 35677547, 2022). "However, pretreatment was sufficient to accelerate the resolution of lung neutrophilia in CF mice, decrease the numbers of Ly6C+ inflammatory monocytes and activated T cells, and normalize the levels of the proinflammatory cytokines IL-6, IL-17, IL-12p70, and IP-10 in BALF samples." (PMID 35581352, 2022). "Thus, IL-6 might play as the protagonist in the pathogenesis of kidney ailment." (PMID 34446789, 2021). "Upon analysis, expression of the cytokines IFNB1, IFNG (IFN-γ), TNF (TNF-α), TGFB1 (TGF-β), IL1B, IL2, IL6, CXCL8 (IL-8), and IL10 were all significantly increased in ‘mesenchymal’ lung ADC compared to ‘epithelial’ tumors." (PMID 29440769, 2018). "Lipopolysaccharide‐induced kidney dysfunction via NF‐κB and MAPK activation, by excessive production of IL‐6, TNF‐α, iNOS, and COX‐2, producing perturbance in energy metabolism and oxidative stress." (PMID 28174688, 2017).
kidney (continued). "In the present study, we have shown that inflammation molecules such as IL-6, TNF-α, MCP-1 and MIP-2 are elevated in IRI kidney." (PMID 28842716, 2017). "In a lipopolysaccharide-induced acute lung injury model, dexmedetomidine improved congestion and edema and reduced the w/d weight ratio and TNF-α, IL-1β and IL-6 levels in lung tissues." (PMID 24345905, 2014). "In a left coronary artery ligation-induced I/R injury model, oral administration of quercetin at 2, 10, or 20 mg/kg for five consecutive days significantly reduced serum and myocardial levels of TNF-α, IL-6, and IL-1β." (PMID 40672380, 2025). "The results showed that the content of propionic acid was negatively correlated with liver lipid accumulation (hepatic TG) and liver inflammation indexes (TNF-α, IL-1β and IL-6), while the content of butyric acid was negatively correlated with liver inflammation." (PMID 35052765, 2021). "The induction of liver IR injury did not affect the tissue concentrations of IL-6 and TNF, however, a significant decrease in the tissue concentration of these cytokines was observed in the HGIR group, compared with both IR and SH groups." (PMID 34824916, 2021). "Similarly, activation of mTORC1 induced by PTEN deficiency promotes the M2 polarization of macrophages and increases the production of IL-10, decreasing the release of TNF-α, IL-6, and IL-12 when responding to TLR stimulation in liver IR injury." (PMID 31827701, 2019). "As for the inflammatory responses, the WBC count and ferritin levels were higher in the kidney injury group (P < 0.01, respectively), whereas the levels of CRP and IL-6 were not significantly different between both groups." (PMID 39840004, 2024). "Evidence has revealed that the absence of TLR4 genes in the liver reduces liver IR injury, and TLR4 blockade affects the function of hepatocytes and Kupffer cells, depresses the production of proinflammatory cytokines (TNF-α and IL-6) and ameliorates hepatocellular IR injury." (PMID 27347929, 2016).